CTLA4 (cytotoxic T-lymphocyte associated protein 4)
Diseases named in the same sentence as CTLA4 in open-access papers (continued):
Sharing a sentence is not in itself a finding about the gene and the disease.
glioma (continued). "Although certain immune checkpoints, including CD274 (PD-L1), PDCD1 (PD-1), and CTLA-4, have been effectively employed in targeted immunotherapy for other organ tumors, this study explored that the expression of these molecules was notably low in gliomas." (PMID 38956740, 2024). "In addition, the combination of humanized L13Rα2 CAR T cells and anti-CTLA4 antibody has been proved to be more effective than single agent in a glioma mouse model." (PMID 37444531, 2023). "As for the role in glioma treatment of immune checkpoint PD-1 and CTLA-4 targeting drugs, for a long time we believed that such drugs could not be used in brain cancer because of the impossibility of reaching glioma cells and microenvironment." (PMID 37371615, 2023). "However, as predicted by our results, CTLA4‐based drugs for the treatment of gliomas have so far been rare due to the low drug responsiveness of gliomas to CTLA4." (PMID 35668574, 2023). "The high-risk group presented a higher expression of PD1 (PDCD1), CTLA4, PD-L1 (CD274), and PD-L2 (PDCD1LG2), and our risk signature could also distinguish glioma patients with similar expression levels of immune checkpoints." (PMID 37004060, 2023). "ICGs, particularly the key members such as CTLA-4 and PD-1, are profoundly involved in immune tolerance and proliferation of glioma cells, and their blockage might inhibit the progression of gliomas." (PMID 36845382, 2023). "Higher CTLA-4 expression is detected in high-grade glioma samples and is caused by a lack of CD80/86 co-stimulatory molecule expression." (PMID 37705736, 2023). "Our signature accurately identifies cool gliomas, which have lower proportions of T-cell infiltration and larger proportions of macrophage infiltration, as well as higher expression of immune checkpoint genes such as CTLA4 and IDO." (PMID 37152037, 2023). "The development of immune targets, including programmed cell death 1 (PD1), cytotoxic T lymphocyte-associated protein 4 (CTLA4), and killer cell lectin-like receptor subfamily B member 1 (KLRB1), lays the groundwork for further tumor-free treatment of glioma." (PMID 37476838, 2023). "This demonstrated that CTLA-4 inhibitory therapy might also improve the prognosis of patients with glioma." (PMID 37837543, 2023). "PD-L1 is also correlated to IgSF11, VISTA and CTLA-4 in high-grade glioma." (PMID 37274252, 2023). "Previous studies found that a monoclonal antibody targeting CTLA-4 (9H10) could reverse immune evasion in well-established murine glioma models." (PMID 36341396, 2022). "The result displayed that majority of the negative immune regulatory genes glioma were upregulated in the high-risk group, and the expression of immune checkpoint CTLA4 and immune checkpoint receptor LAG3 was notably higher in the high-risk group." (PMID 39279987, 2022). "However, this trend appears inconsistent in glioma as inhibitory immune checkpoints such as PD-1, CTLA-4 and TIM-3 are consistently upregulated in M1/M2 GAMs which have been shown to significantly decrease patient prognosis." (PMID 35711434, 2022). "PD-1, PD-L1, and CTLA-4 are the main immune checkpoint molecules in glioma immunotherapy." (PMID 36060266, 2022). "Moreover, the same analyses were performed on the expression levels of CTLA4, PD1, PDL1 and PDL2, which were significantly related with the OS of glioma patients and increased in the high-risk group (p < 0.001)." (PMID 35719378, 2022). "Research indicates therapeutic effects for anti-PD1 and anti-CTLA4 therapies in glioma." (PMID 35372082, 2022). "However, triple combination of HSV armed with IL-12 along with anti-CTLA-4 and anti-PD-L1 increased influx of macrophages and M1 polarization and was very effective in curing both murine glioma models including aggressive carcinogen-induced tumors." (PMID 35163730, 2022).
glioma (continued). "Besides, we also proved that high-ITGA5 gliomas were accompanied by high immunotherapy biomarker expression, namely, PD-1, PD-L1, CTLA-4, and VEGF, thus showing an ITGA5-targeted therapeutic potential to be synergistic with immunotherapy." (PMID 35371978, 2022). "CTLA-4 overexpression in glioma TME can induce immune cell infiltration." (PMID 36712869, 2022). "Studies on CTLA-4 immunosuppressants have also shown good effects in patients with glioma." (PMID 36466873, 2022). "LINC00346 high-expression gliomas were more sensitive to the anti–PD-1 and anti-CTLA-4 therapy." (PMID 36311792, 2022). "In this study, the response of CTLA4 and PD-1 treatment in glioma was evaluated, and difference was found between high- and low-grade glioma groups, hinting that anti-CTLA4 or anti–PD-1 drugs might be a good method for high-grade glioma patients." (PMID 36311792, 2022). "The therapeutic suppression of PD-L1, IDO, or CTLA-4 lowers the number of tumor-infiltrating Treg cells and improves long-term permanence, whereby a blockade of safety checkpoints can be considered an encouraging approach in glioma immunotherapy." (PMID 36146527, 2022). "These consequences indicated that CTLA-4 blockade could be rational modalities of restoring glioma-induced variations to the CD4 compartment and eliciting antitumor immunity." (PMID 35392976, 2022). "Also, our combination gene therapy together with CTLA4, or anti-PD-L1 immune-checkpoint blockade significantly increased the survival of glioma-bearing animals." (PMID 36186781, 2022). "Besides, we also made an analysis of the relationship between differential LOXs expressions and the expressions of immune checkpoints including PD-L1, PD-1, IDO-1, and CTLA4 in glioma." (PMID 36160460, 2022). "Those gliomas in CRGRS high-risk group would harbor more immune cell infiltration, express more immunotherapy targets (including PD-1, PD-L1, CTLA4, and B7H3), and therefore could potentially present a better response to immunotherapy." (PMID 36267281, 2022). "Moreover, Foxp3+ Tregs in glioma can bind to CD80/CD86 on antigen-presenting cells (APCs) through CTLA-4, affecting their efficacy and thus inhibiting T lymphocyte activity." (PMID 36466873, 2022). "In the present work, most of these exhaustion markers [TIGIT, CEACAM1, CTLA4, LAG3, PD-1, PD-L1, and TIM3] were highly expressed in the high-risk subtype, indicating an elevated level of immune exhaustion in the tumors of high-risk glioma patients." (PMID 34778248, 2021). "More importantly, the expression of CTLA-4 is correlated with the glioma grade." (PMID 34006227, 2021). "Thus, we especially assessed the relationship of MK3 with PD-1, PD-L1, and CTLA-4 in glioma by using TIMER tool." (PMID 34938665, 2021). "Similarly, we also found that the expression of MK3 was significantly positively correlated with PD-1 (r = 0.520, p < 0.001), PD-L1 (r = 0.570, p < 0.001), and CTLA-4 (r = 0.360, p < 0.001) in glioma." (PMID 34938665, 2021). "Based on TCGA and CGGA datasets, we observed a high and positive correlation between TNFSF13 and PDCD1LG2, HAVCR2, CTLA4, and other checkpoint molecules in pan-gliomas, LGG and GBM analysis, and TNFSF13 expression is tightly correlated with HAVCR2 in glioblastomas." (PMID 34712225, 2021). "Moreover, we found that CTLA-4 was positively correlated with other immune-related proteins in glioma." (PMID 31911758, 2020). "Consequently, we also explored the prognostic value of CTLA-4 expression in patients with low-grade gliomas (LGGs)." (PMID 31911758, 2020). "Furthermore, administration of 1-methyl-tryptophan (an IDO inhibitor) in combination with PD-L1 and CTLA-4 inhibitors resulted in 100% glioma mice survival, improved over PD-L1 and CTLA-4 dual inhibitor therapy." (PMID 31973059, 2020). "CTLA-4 was reported to highly expressed in high grade gliomas." (PMID 31911758, 2020). "Therefore, we divided patients with glioma into low- and high-expression groups to evaluate the prognostic value of CTLA-4." (PMID 31911758, 2020).
glioma (continued). "Additionally, clinical trials of anti-CTLA-4 (ipilimumab) and anti-PD-1 (nivolumab) have also been performed in patients with glioma." (PMID 31911758, 2020). "In TCGA database, higher expression of CTLA-4 was detected in higher grade glioma samples." (PMID 31911758, 2020). "The highest CTLA-4 expression was found in WHO grade IV glioma (glioblastoma)." (PMID 31911758, 2020). "In summary, our findings revealed the expression patterns and clinical characteristics of CTLA-4 in glioma and may be helpful for expanding our understanding of antitumor immunotherapy in gliomas." (PMID 31911758, 2020). "Patients with glioma with lower CTLA-4 expression exhibited significantly longer overall survival." (PMID 31911758, 2020). "Combined with immune checkpoint inhibitors targeting PD-1/PD-L1, antibodies that block CTLA-4 may have applications as immunotherapies for the treatment of various malignancies, including glioma." (PMID 31911758, 2020). "Previous studies using oncolytic viruses to treat glioma led us to hypothesize that inhibitory receptors may be blunting the anti-tumor immune response, so we also added anti-CTLA-4 and anti-PD1 combination immune checkpoint blockade (ICB)." (PMID 31315671, 2019). "With the addition of cytotoxic T-lymphocyte-associated protein 4 (CTLA-4) blockade, the combination of 4-1BB activation and radiation further improved survival in GL261 murine glioma model, which is associated with greater infiltration of CD4+ and CD8+ lymphocytes." (PMID 30558196, 2018). "The critical roles of CTLA-4 in regulating immunosuppressive antitumor responses have been illustrated in glioma, which suggest that anti-CTLA-4 treatment will largely enhance CD4+ T-cell proliferation and restore the Treg/CD4+ ratio to further support the antitumor response." (PMID 30619286, 2018). "Accordingly, a subset of patients with recurrent high-grade glioma may benefit from anti-CTLA-4 treatment." (PMID 27756892, 2017). "More importantly, the expression of CTLA-4 is correlated with the glioma patients’ progression." (PMID 27756892, 2017). "The role of CTLA-4 in glioma maintenance is complex and incompletely understood." (PMID 26881264, 2016). "Interestingly, administering 1-MT with anti-CTLA-4 and anti-PD-L1 monoclonal antibodies produced a 100% long-term survival rate in glioma-bearing mice, an improvement over the 90% long-term survival rate in anti-CTLA-4 and anti-PD-L1 therapies alone." (PMID 26217588, 2015). "Another possible approach to reduce Tregs in glioma is via CTLA-4 blockade." (PMID 25009822, 2014). "Combination therapy with RT and CTLA-4 blockade improved survival in our glioma model." (PMID 25013914, 2014). "In preclinical mouse glioma models, systemic blockade of CTLA-4 exhibited increased survival." (PMID 24202450, 2013). "On the other hand, m6A-modified CTLA-4 has been correlated with increased expression of CTLA-4 expression in gliomas, implicating that some tumors may exploit RNA modifications to gain a competitive advantage towards immune suppression rather than T-cell activation." (PMID 40565233, 2025). "Although HGGs are generally “cold tumors” due to its relatively low T cell infiltration in comparison with other tumors, ICI development is still may be a valid approach in gliomas, as CTLA-4, PD-1, TIM3, LAG3 and their corresponding ligands are expressed in these tumors." (PMID 36186781, 2022). "Moreover, LYN expression in glioma patients could significantly predict anti-PD-1 and anti-CTLA-4 immunotherapy responses based on the TIDE algorithm." (PMID 35186945, 2021). "Furthermore, the differential expression of PD-L1 and CTLA-4 were compared between lower-grade gliomas (LGGs; tumour grade II ∼ III) and glioblastoma in the high-risk group, and between different risk groups within the same tumour grade, such as PD-L1-grade IV-Low risk V.S. PD-L1-grade IV-High risk." (PMID 35127714, 2021).
glioma (continued). "Fortunately, the expression levels of PDCD1 (PD-1), CD274 (PD-L1), and CTLA4, the vital immune checkpoints in glioma, were significantly higher in IS2 than other subtypes, which indicated that patients receiving ICIs therapies might achieve a better curative effect." (PMID 34404444, 2021). "Thus, CTLA-4 is a promising novel target for glioma treatment." (PMID 34298735, 2021). "Subsequently, we investigated whether PDIA5 could predict glioma patients’ responses to checkpoint inhibitor immunotherapy in anti-CTLA-4 and anti-PD-1 based on CGGA and TCGA datasets, and found that compared with low PDIA5 group, high PDIA5 group was expected to respond better to immunotherapies." (PMID 33664747, 2021). "Our findings showed that CTLA-4 may serve as a good predictor for mesenchymal subtype glioma." (PMID 31911758, 2020). "Notably, CTLA-4 is found only on T-cells; therefore, low levels of this transcript may represent differences in the T-cell populations within canine gliomas compared to other species." (PMID 29352201, 2018). "This novel approach allows the compatibility with blocking antibodies for other immune checkpoints (such as anti-CTLA-4) as well as targeting gliomas, since the patch could be directly delivered to the capillary bed within the brain, bypassing the blood-brain barrier." (PMID 27756892, 2017). "CTLA-4 is not only associated with glioma progression and prognosis, the CTLA-4 A49G polymorphism might also be a potential clinically relevant biomarker for distinguishing individuals with a high risk for developing glioma." (PMID 23720663, 2013). "Tumor and peripheral blood samples from 32 glioma patients (WHO 2021 classification, grades II-IV) were analyzed by flow cytometry to assess ILC subsets and immunecheckpoint molecules (PD-1, CTLA-4, KLRG1)." (PMID 41917320, 2026). "In co-culture assays, IDH1-mutant glioma cells and their GCM suppressed PD-1 and CTLA-4 expression on ILCs while promoting proliferation." (PMID 41917320, 2026). "Some other immune checkpoints, including CTLA-4, CD47, CD73, TIGIT, and CD137 were also studied in either clinical trials or preclinical research for gliomas." (PMID 39851525, 2025). "Cellular metabolic changes in lymphocytes co-cultured with glioma explants were assessed by FLIM in response to immunotherapy with anti-PD-1/PD-L1 and anti-CTLA-4 antibodies and their combination." (PMID 39851525, 2025). "Combining CTLA-4 blockade with IL-12 enhanced TH1 polarization, achieving complete remission in glioma-bearing mice." (PMID 39911397, 2025). "Notably, we observed that CTLA-4+ cell infiltration is significantly associated with poor PFS, indicating that CTLA-4-related immune suppression may be a dominant immune escape mechanism in central nervous system tumours." (PMID 41285059, 2025). "Immune checkpoint genes such as PD-L1, PD-1, CTLA4, LAG3, HAVCR2, PDCD1LG2 were positively correlated with IGFBP5 in glioma." (PMID 38164271, 2024). "Our data revealed a significant correlation between the expression levels of immune checkpoint molecules (CD274, CTLA4, HAVCR2, LAG3, PDCD1, PDCD1LG2, TIGIT, and SIGLEC15) and RAB32 in high-grade gliomas (HGG)." (PMID 39668831, 2024). "The investigation revealed considerable similarities between SOCS1 and several immune checkpoints such as CTLA4, demonstrating SOCS1’s role as an independent prognostic factor positively influencing glioma patient outcomes." (PMID 39654174, 2024). "In our study, Siglec15 was broadly and positively correlated with immune checkpoints that have been reported as potential biomarkers of glioma, such as PD1, PDL1, PDL2, Lag3, CTLA4, TIGIT, CD276 (B7-H3), IDO1 and CD47." (PMID 37325664, 2023). "The scarcity of T and NK cells within the glioma TME is one of the reasons why immunotherapies, such as CTLA-4 and anti-PD-1/L1, are ineffective." (PMID 37345193, 2023).
glioma (continued). "Other than PD-1 and CTLA-4, indoleamine 2,3-dioxygenase-1 (IDO-1) as well as T cell immunoglobulin and mucin domain 3 (TIM-3) have recently come to the forefront in glioma immunotherapy." (PMID 37046685, 2023). "We further analyzed the expression distribution of immune checkpoints gene (including CD274, CTLA4, HAVCR2, LAG3, PDCD1, PDCD1LG2, TIGIT, and SIGLEC15) in glioma tissues and normal brain tissues using the TCGA database." (PMID 36915038, 2023). "Considering the potential oncogenic role of REST in glioma, the relationship of REST with PD1, PD-L1, or CTLA-4 was assessed." (PMID 36810892, 2023). "Moreover, a positive correlation was identified between the risk score and immune checkpoints, namely CTLA4, HVEM, CD200R1, PD-1, and TIM-3, which are implicated in tumor-mediated immunosuppression and evasion, akin to the role of microglia and macrophages in glioma." (PMID 38137116, 2023). "We observed that PTPN18 expression was positively correlated with six immunosuppressive genes (PD-L1, PD-1, CTLA4, LAG3, HAVCR2, and CD244) in most cancers, including glioma." (PMID 36846716, 2023). "Given that the potential carcinogenic effects of PLEKHA4 in glioma, the relationships between glioma and PD1, PD-L1, CTLA-4, and TIM-3 were analyzed." (PMID 36714030, 2023). "We found that cluster 2 had a remarkably high expression level of most of the immune checkpoints including PD-1 (PDCD1), PD-L1 (CD274), and CTLA-4 (CD276), and most of these trends were consistent between IDH-mutant and IDH-wildtype gliomas." (PMID 36970537, 2023). "Our study found that several immune checkpoints (BTLA, CD200R1, PD-L1, B7-H3, CD70, CTLA4, IDO1, and PD1) in patients with CDC42 high expression glioma were upregulated compared to the CDC42 low expression group." (PMID 37476838, 2023). "Checkpoint molecules, including PD-L1, CTLA-4, and IDO, have been demonstrated to be involved in the immune escape of glioma cells." (PMID 37325664, 2023). "A durable survival benefit was achieved utilizing combinatorial blockade against CTLA-4, PD-L1 and indoleamine 2,3 dioxygenase 1 (IDO) in glioma-bearing mice models." (PMID 35428347, 2022). "Multiple studies have identified immune targets for glioma immunotherapy, mainly focusing on co-inhibitory checkpoints, including PD1/PD-L1 and CTLA4." (PMID 36276141, 2022). "Intriguingly, RAB34 exhibited closely positive relationship with these immune checkpoints (PD-1, PD-L1, CTLA4, PD-L2, TIM-3, and B7-H3) in all grade gliomas in TCGA and CGGA cohorts as shown by Circos plots." (PMID 36222286, 2022). "The results showed that significant positive correlations existed between MELK expression and B7-H3, CTLA4, LAG3, PD-1, PD-L1, and TIM3 expression in glioma." (PMID 36353126, 2022). "In glioma, the therapeutic suppression of PD-L1, IDO, or CTLA-4 lowers the amount of tumor-infiltrating Treg cells and improves long-term permanence." (PMID 36146527, 2022). "It is found that the expression of PROS1 had positive correlations with PD-1, PD-L1, PDCD1LG2, CTLA4, HAVCR2, and GZMB (all P <0.05) in glioma." (PMID 36685506, 2022). "Notably, the mice with glioma and an overexpression of vascular endothelial growth factor C (VEGF-C) displayed better responses to the anti-tumor therapies, including combinations of the anti- programmed death-1 protein (PD1) and cytotoxic T-lymphocyte-associated protein 4 (CTLA-4) blockade." (PMID 36559105, 2022). "To analyze the TIME characteristics of different pyroptosis subtypes, we compared PD-L1 expression, CTLA4 expression, mRNAsi score, TMB score, MSI score, immune score, stromal score, and infiltrating cells in the three glioma sample clusters." (PMID 35784306, 2022). "PIMREG correlated with CTLA-4, PDCD1, LAG3 and other immune checkpoints in glioma and correlated with the patient’s response to immunotherapy." (PMID 35928818, 2022).